IL6 (interleukin 6)
Diseases named in the same sentence as IL6 in open-access papers (continued):
Sharing a sentence is not in itself a finding about the gene and the disease.
breast cancer (continued). "In this study, we demonstrated that TG2 expression levels are correlated with cancer cell aggressiveness, and that the size and efficiency of tumor sphere formation was correlated with TG2 expression levels and was dependent on TG2-mediated IL-6 secretion in breast cancer cells." (PMID 21967801, 2011). "All 5 significantly up-regulated pathways were Identical to human breast cancer the cell cycle, G1 to S control reactome and DNA replication reactome pathways were up-regulated, whereas striated muscle contraction and IL-6 pathways were significantly down-regulated." (PMID 21062462, 2010). "This study contributes to recent literature supporting the notion that epigenetic modifications driven by IL-6 are of relevance to determine the gene expression profile of cancer cells, and we can conclude that IL-6 blockage holds promises as a potential therapeutic strategy to combat breast cancer." (PMID 21092249, 2010). "Furthermore, IL-6 has been shown to promote an epithelial-mesenchymal transition in breast cancer which correlated with enhanced invasion." (PMID 20929542, 2010). "In addition, based on work by Ndlovu and colleagues, NF-κB was shown to increase chromatin accessibility across the IL-6 promoter in breast cancer cells." (PMID 20814569, 2010). "It was recently determined that exogenous sources of IL-6 could enhance autocrine production of IL-6 in models of breast cancer where IL-6/pStat3 levels were very low." (PMID 20929542, 2010). "Notably, a recent publication implicated IL-6 as a critical regulator of tumor stem cell renewal, by showing that IL-6 treatment promoted growth of mammospheres formed by MCF-7 cells and primary breast cancer cells." (PMID 20637104, 2010). "In addition, IL-6 administration elicits the gain of methylation at ERα promoter, whose epigenetic regulation is of primary importance in breast cancer biology." (PMID 21092249, 2010). "In addition, we show that BITC can prevent the induction of STAT3 activation by Interleukin-6 in MDA-MB-453 breast cancer cells." (PMID 19712481, 2009). "In contrast to MSC inhibiting tumor progression and similar to what is described within this paper, our previous data shows that MSC can enhance the growth rate of a subpopulation of breast cancer cells in vitro and in vivo through paracrine interleukin-6 (IL-6) signaling events." (PMID 19352430, 2009). "It is conceivable that BST2 may be an important regulator in the STAT3/BST2/IL6 pathway leading to increased cell migration and proliferation in the bone metastatic breast cancer." (PMID 19338666, 2009). "Furthermore, we have identified two possible biomarkers (IL-1β and IL-6) for assessing the efficacy of anti-VEGF therapy in breast cancer patients." (PMID 19888452, 2009). "High levels of IL-6 have been found in many human breast cancers." (PMID 18728665, 2008). "Since bone is the primary site for metastasis in breast cancer patients, these results suggest IL-6 may be a major factor contributing to tumor growth and metastasis." (PMID 18939993, 2008). "However, this correlates well with the greater level of IL-6 production from MDA-MB-231 breast cancer cells compared to MDA-MB-468 breast cancer cells." (PMID 18939993, 2008). "Further, IL-6 is a potent growth factor for ER-α positive human breast cancer." (PMID 18939993, 2008). "In addition, mesenchymal stem cells, which are a major component of the fibroblast cell population in bone marrow, have recently been identified to secrete IL-6 in a paracrine fashion to enhance growth in ERα+ breast cancer cell lines." (PMID 18939993, 2008). "We propose that the IL-6/gp130/Jak signaling pathway plays a critical role in Stat3 activation in human breast cancer and that blockade of this pathway may be an important therapeutic modality in breast cancer." (PMID 17531096, 2007). "IL-6 was recently shown in breast cancer cells to activate ER and this could lead to increased ERα expression." (PMID 17118173, 2006).
breast cancer (continued). "The aim of this study was to evaluate polymorphisms in specific cytokine genes [IL1A +4845G>T, IL1B -511C>T, IL1B +3954C>T, IL1RN +2018T>C, IL4R -1902A>G, IL6-174G>C and IL10-1082G>A] in a case control model to determine any associations with breast cancer susceptibility, severity and survival." (PMID 16842617, 2006). "Interleukin 6 (IL-6) is secreted by breast tumours and shows synergistic activity with 17β-oestradiol (E2), leading to increases in reductive 17β-hydroxysteroid dehydrogenase activity in breast cancer epithelial cells." (PMID 10755407, 2000). "Therefore, the effects of MPA on IL-6 secretion were studied both in vitro and in vivo using a human breast cancer cell line, KPL-4, which secretes IL-6 into medium and induces cachexia when injected into female nude mice." (PMID 10027341, 1999). "However, IL-6 exhibits complex and sometimes contradictory effects on breast cancer cells." (PMID 41226910, 2025). "Consequently, these compressed breast cancer cells secrete more IL-6 cytokines into the tumour microenvironment where it then functions in autocrine and paracrine manners to upregulate downstream gene targets of IL-6 such as SNAI1." (PMID 40371393, 2025). "Therefore, we hypothesise that the upregulation of SNAI1 protein levels observed in compressed breast cancer cells could be due to the solid stress-induced upregulation of IL-6." (PMID 40371393, 2025). "For example, therapeutic blockade of IL-6 and IL-8 in mice using Tocilizumab (a humanised monoclonal antibody against the α chain of IL-6) and Reparixin (a low-molecular-weight inhibitor of IL-8 signalling) seems to be very effective in suppressing breast cancer metastasis in experiments." (PMID 41009413, 2025). "For instance, Leptin and Insulin levels decreased, particularly in Breast cancer patients, whereas Colorectal cancer patients exhibited a reduction in pro-inflammatory cytokines such as IL-1β, IL-6, IL-8, and TNF-α, even in the absence of weight loss and bioimpedential feature changes." (PMID 41409302, 2025). "Therefore, high levels of IL-6 correlate with a poor prognosis for breast cancer patients." (PMID 40043049, 2025). "Interestingly, this phenomenon simulates the changes in breast cancer cells after senescence and increasing IL-6 and IL-8 levels in the microenvironment results in the “self-circulation pathway” to promote the acquisition of a stemness phenotype in cancer cells." (PMID 38540708, 2024). "Furthermore, tGLI1 and IL-6/IL-6R/GP130 were significantly co-activated in HER2-enriched breast cancer and TNBC when compared to luminal patients, as validated by two separate breast cancer datasets, The Cancer Genome Atlas (TCGA) and the Gene Expression Omnibus (GEO)." (PMID 39768178, 2024). "Interestingly, it has been shown in breast cancer patients and mouse models that circulating tumor cells form clusters with neutrophils in the blood releasing cytokines such as IL-6 or G-CSF, which drives tumor proliferation and increases their metastatic potential." (PMID 38419052, 2024). "However, the expression of FOXA1 and ERα has decreased in TAM-R breast cancer cells, but the activation of transcription factor nuclear factor-κb (NF-κB) and the expression of its target protein IL6 is increased in these cells, contributing to cancer stem cell properties of TAM-R cells." (PMID 38605023, 2024). "For example, breast cancer cells may secrete cytokines such as interleukin-6 (IL-6) and interleukin-8 (IL-8) which trigger signaling pathways involved in immune evasion, cell proliferation, angiogenesis, breast cancer chemoresistance, and epithelial-mesenchymal transition (EMT)." (PMID 38314029, 2024). "In estrogen receptor-positive breast cancer (ER+ BC, of any stage) patients, we found that ~40% harbor defects in immune signaling at the time of diagnosis, including altered signaling responses to IL-6, IFNγ, TGFβ, IL-10, and IL-4 in various immune cells." (PMID 39389979, 2024).
breast cancer (continued). "The results of the current study confirm that 1,25(OH)2D inhibits the migratory potential of breast cancer cells and that this may be due in part to an indirect mechanism—by altering adipocyte release of chemoattractants, such as leptin, adiponectin, IL-6, and IGF-1." (PMID 39339753, 2024). "Due to the clinical evidence that co-activation of the tGLI1 and IL-6/IL-6R/GP130 signaling pathways is associated with more aggressive subtypes in breast cancer patients, we next examined the role of tGLI1 and GP130 in the HER2-enriched breast cancer and TNBC stem cell subpopulation in vitro." (PMID 39768178, 2024). "Notably, neutralising antibodies against IL‐6 and IL‐8 can reverse the effects of senescent cell‐conditioned medium on the breast cancer cell line MCF‐7, highlighting these cytokines act as pivotal mediators of EMT and stemness‐related effects within the senescent microenvironment." (PMID 39270064, 2024). "Finally, we only investigated the causal relationship between CRP, IL-1, IL-6 expression levels and breast cancer risk, without analyzing other biomarkers of chronic inflammation and transcription factors, which are also crucial for breast cancer occurrence." (PMID 38263420, 2024). "Similarly, a combination of resistance and high-intensity interval training in women with breast cancer undergoing chemotherapy was found to be more effective in decreasing plasma IL-6 levels, as compared with concurrent moderate-intensity aerobic and high-intensity interval training." (PMID 38136400, 2023). "Therefore, we checked whether Grem2 overexpression in adipocytes also affected the reduction of IL-6 expression in breast cancer cells." (PMID 37880751, 2023). "The authors also proposed that the expression of ER and phosphorylated STAT3 (pSTAT3) may be considered independent prognostic factors in breast cancer, and that targeting IL-6/STAT3 could have clinical potential in ER-positive, endocrine therapy-refractory patients." (PMID 37834225, 2023). "However, the molecular mechanism by which breast cancer-secreted IL-6 regulates the expression of KDM2A remains unclear." (PMID 37821959, 2023). "TAMs can play a role in endocrine resistance; for example, macrophages may induce endocrine resistance in ER+ breast cancer cells by inducing sustained release of TNF-α and IL-6 from breast cancer cells, resulting in activation of NFκB, STAT3, and ERK-1 and hyperphosphorylation of ERα." (PMID 36909339, 2023). "Indeed, IL-6 may up-regulate circulating VEGF in breast cancer patients and promote angiogenesis and metastasis." (PMID 36835413, 2023). "However, the detailed molecular mechanism by which IL-6 regulates KDM2A in breast cancer remains unclear." (PMID 37821959, 2023). "Interestingly, IL-6 was also positively correlated with IL-8 in MCF7 cells, and these cytokines have been linked to the metastatic process, including the priming of the pre-metastatic niche in breast cancer." (PMID 38136303, 2023). "The results showed that the addition of IL6 neutralizing antibodies could abrogate the enhanced effect of supernatants from HSPB1 overexpressing cells on THP1 migration, suggesting the involvement of HSPB1-IL6 pathway in the regulation of accumulation of macrophages in breast cancer." (PMID 37454220, 2023). "As both IL-6 and IL-8 have been reported to be involved in the formation and stimulation of the cancer stem cell phenotype in various cancers, we used the mammosphere formation assay to confirm the effect of IL-6 and IL-8 on the cancer stem cell population in breast cancer." (PMID 38136303, 2023). "Therefore, the effect of IL-6 on breast cancer cells has been inconsistent." (PMID 36794014, 2023). "Moreover, resistance exercise in breast cancer patients undergoing treatment inhibited the increase in IL-6 and IL-6/interleukin-1 receptor antagonist (IL-1ra) ratio, which were associated with high levels of physical fatigue and pain in the control (non-exercising) group." (PMID 38136400, 2023).
breast cancer (continued). "However, IL-6 receptors IL-6Rα and gp130 were found to be reduced on naïve CD4+ T cells from breast cancer patients compared to healthy donors by flow cytometry, and expression levels correlated with signaling responsiveness to IL-6, identifying a potential mechanism of impaired signaling." (PMID 37741983, 2023). "Ascites proinflammatory cytokines IL-1β, IL-6, TNF-α were increased in model mice, but were significantly reduced following EFL1 or DOX administration, which demonstrates that EFL1 is able to decrease the generation of proinflammatory cytokines caused by breast cancer liver metastasis." (PMID 37709489, 2023). "Indeed, some studies considered IL-6 as a potential marker in the prognosis of breast cancer." (PMID 36980857, 2023). "MDD is associated with higher circulating levels of inflammatory cytokines, such as interleukin (IL)‐6, IL‐8, IL‐1β, TNF‐α, soluble IL‐2 receptor (sIL‐2R), and C‐reactive protein (CRP), which promote cellular proliferation in breast tissue and have also been linked to development of breast cancer." (PMID 35852181, 2023). "Therefore, we hypothesized that IL-6 mediated the CAF-induced radioresistance of breast cancer cells." (PMID 36635302, 2023). "Therefore, targeting the PDGFRA/STAT3/IL-6 pathway using PDGFRA inhibitors might serve as a therapeutic option to reduce tumor aggressiveness in HER2+ breast cancer." (PMID 36979654, 2023). "Addressing the mechanism underlying Th22 cell recruitment, using 4T1-IL-6-KO mouse mammary carcinoma, they observed that in the absence of IL-6, total CD4+ helper cells including Th17 significantly expanded in the tumors, whereas Th22 and MDSC frequencies reduced in all tissues." (PMID 37835465, 2023). "Similarly, IL-6 was proved to be essential in keeping inflammatory loop in breast cancer CSCs." (PMID 35924148, 2022). "After adjustment for BMI, associations between leptin, adiponectin and leptin/adiponectin ratio and breast cancer risk were no longer significant, while a significant positive association was observed for IL-6 (ORper SD increment = 1.32 (1.12–1.55); ORQ4vsQ1 = 1.55 (1.04–2.30), P-trend = 0.01)." (PMID 35948877, 2022). "Therefore, targeting Angiotensin initiation of NF-kB/IL-6/JAK2/STAT3 pathway could be a beneficial strategy in breast cancer therapies." (PMID 36431925, 2022). "Moreover, the role of modulating differentiation by IL-6 was also examined in the breast cancer." (PMID 36405712, 2022). "However, the correlation between IL-6 and IL-12 remains elusive in breast cancer." (PMID 35924148, 2022). "This may provide a potential therapeutic target for breast cancers with high IL-6 expression." (PMID 35242126, 2022). "Moreover, genistein can influence metastasis and induce apoptosis by inhibiting Akt, as well as NF-κB cascades, in PC3 cell lines and MDA-MB-231 breast cancer cell lines, as well as inhibiting the IL-6/STAT3 pathway in MDA-MB-453 breast cancer cell lines, thus inhibiting cell proliferation." (PMID 35956766, 2022). "Thus, among the pro-inflammatory cytokines in breast cancer, the content of IL-1β, IL-2, and IL-6 increased (+16.1%, +25.0%, and +12.7%, respectively), while for TNF-α, MCP-1, IL-8, and IL-18, the content decreased (−36.2%, −23.8%, −15.0%, and −12.1%, respectively)." (PMID 36286034, 2022). "In the fully adjusted model (which included BMI but not waist circumference), IL-6 was positively associated with breast cancer risk (continuous variable only, ORper SD increment = 1.33 (1.11–1.60)), as was TNF-α (ORper SD increment = 1.32 (1.11–1.58); ORQ4vsQ1 = 2.03 (1.26–3.26), P-trend = 0.006)." (PMID 35948877, 2022). "Thus, Tamm and colleagues asked whether IL-6 stimulated the proliferation of breast cancer cells T47D and ZR-75-1 and/or affected the cancer-cell phenotype." (PMID 35406728, 2022).
breast cancer (continued). "Indeed, sympathetic stimulus has been described to increase IL-6 levels in MDA-231 breast cancer cells with high β-adrenergic receptor (β-AR) expression and both MDA-1833 and human osteoclasts express several ARs, being therefore responsive to sympathetic stimuli." (PMID 35243294, 2022). "Hence, targeting the ORAI1/STIM1 function in basal breast cancer cells could lead to a decrease in overall inflammatory signals through its effect on IL6 and PTGS2 expression." (PMID 35682546, 2022). "Thus, our data suggests that breast cancer cells induce IL-6 expression in activated macrophages." (PMID 35300689, 2022). "Glioblastoma and breast cancer cells are reported to secrete a variety of paracrine factors: these cancer cells release extracellular vesicles, carrying molecules such as proteins and microRNAs, vascular growth factors, IL-6,8, all of which play a role in inducing the BBB breakdown." (PMID 35406760, 2022). "Additionally, isolated fibroblasts from breast tissue and breast cancer metastases secrete significantly more IL-6, enhance breast cancer cell growth, and induce pSTAT3 when compared to normal skin fibroblasts supporting IL-6’s role in priming the “soil” for organ-specific metastasis." (PMID 35371975, 2022). "In addition to interferon, the TME of AA women with breast cancer has a higher abundance of the pro-inflammatory markers IL6 and resistin compared to EA women which could contribute to racial disparities in clinical outcomes." (PMID 34071280, 2021). "In vitro dormancy model of MCF-7 breast cancer cells, bone marrow stroma secretory senescence (IL-6, IL-8, and TGFβ1) could reactivate dormant MCF-7 cells by promoting their phenotype to mesenchymal appearance, resulting in cellular proliferation and migration." (PMID 34458273, 2021). "It was previously reported in a clinical trial that breast cancer patients may enjoy a good prognosis by reducing the serum levels of inflammatory factors IL-6, IL-8, and TNF-α, and this might even offer protection from the metastases and recurrence of breast cancer." (PMID 34485118, 2021). "Overall, these data expand our previous findings of an Sdc-1-dependent modulation of a CSC phenotype in breast cancer cells via the IL6/STAT3-, Wnt- and Notch-pathways and suggest that Sdc-1 knockdown may induce differentiation of the CSC population, thus attenuating malignant properties." (PMID 34070901, 2021). "We therefore hypothesized that ERα in breast cancer cells could mediate the expression of IL-6." (PMID 33806019, 2021). "Consequently, the migration potential of the breast cancer cells increases through IL-6 treatment." (PMID 34944905, 2021). "This may provide a potential therapeutic target for the treatment of IL-6 (high) breast cancer." (PMID 34829498, 2021). "Moreover, according to these results, we suggest that the high expression of IL-6 in PBMCs may be considered as a new potential biomarker for the detection of breast cancer." (PMID 33517609, 2021). "Additionally, infiltrated MDSCs might facilitate the shedding of IL-6 receptor, eventually promoting invasion and metastasis of breast cancer cells via IL-6 trans-signaling." (PMID 33957948, 2021). "In the present study, we further demonstrate that 13R,20-diHDHA has potential anti-inflammatory effects and can inhibit breast cancer stemness by inducing ROS production to alter Stat3/IL-6 signaling, and thus may be a promising potential therapeutic agent acting against breast CSCs." (PMID 33804152, 2021). "Indeed, this model could also be translated into the setting of breast cancer bone metastasis, where increased levels of IL-6 and IL-8 in the bone environment could act as chemoattractants for CTCs." (PMID 33809315, 2021). "The results showed that the secretion of TNF-α, IL-6 and IL-1β were all decreased after AT-I treatment, and we concluded that AT-I could suppress tumorigenesis in breast cancer via inhibiting TLR4/NF-κB pathway, and down-regulate downstream pro-inflammatory cytokines." (PMID 33363472, 2020).